ST6GAL1 (ST6 beta-galactoside alpha-2,6-sialyltransferase 1)
Diseases named in the same sentence as ST6GAL1 in open-access papers (continued):
Sharing a sentence is not in itself a finding about the gene and the disease.
thyroid cancer (2 papers, 2022 to 2023). "In spite of this, the involvement of ST6GAL1 in the development of thyroid cancer was poorly studied." (PMID 38003522, 2023). "We analyzed the microarray data of the TCGA database to investigate the role of ST6GAL1 mRNA levels in thyroid cancer progression." (PMID 38003522, 2023). "The strength of our current study is that we analyzed the ST6GAL1 protein expression in different types of well-differentiated thyroid cancers." (PMID 38003522, 2023). "Data from the Human Protein Atlas portal showed an increase in ST6GAL1 expression in thyroid cancer." (PMID 38003522, 2023). "The scope of future studies should be the elucidation of ST6GAL1—Tg interaction in thyroid cancers and other thyroid diseases." (PMID 38003522, 2023). "In this study, we analyzed the ST6GAL1 protein expression in different types of well-differentiated thyroid cancers and showed ST6GAL1 protein overexpression in all thyroid tumors compared to normal thyroid tissue." (PMID 38003522, 2023). "The scope of future studies should be clarification of molecular pathways through which ST6GAL1 is involved in thyroid cancer." (PMID 38003522, 2023). "Since Tg levels are altered in thyroid pathologies, in the current study, we wanted to evaluate the expression of ST6GAL1 in thyroid cancer tissues." (PMID 38003522, 2023). "TCGA data also showed elevated ST6GAL1 mRNA expression in FVPTC and a high association with lymph node metastasis status, clinical stage, and shorter overall survival in thyroid cancers." (PMID 38003522, 2023). "However, although 116 cases showed high ST6GAL1 expression in thyroid cancer, 385 cases had low ST6GAL1 expression." (PMID 38003522, 2023). "Moreover, our recent study observed an increase in ST6GAL1 in various well-differentiated thyroid carcinomas (I.G., unpublished data)." (PMID 35216288, 2022). "Although different types of thyroid cancer were included in this project, an analysis of ST6GAL1 expression between different types of thyroid cancers was not conducted." (PMID 38003522, 2023). "ST6 β-galactoside α2,6-sialyltransferase 1 (ST6GAL1) has been studied in various types of cancers; however, the expression and function of ST6GAL1 in thyroid cancer has not been investigated so far." (PMID 38003522, 2023). "Thus, the authors pointed out that ST6GAL1 is not prognostic in thyroid cancer." (PMID 38003522, 2023).
triple-negative breast carcinoma (2 papers, 2023 to 2025). An invasive breast carcinoma which is negative for expression of estrogen receptor (ER), progesterone receptor (PR), and human epidermal growth factor receptor 2 (HER2). "ST6GAL1 correlates with advanced stage, chemoresistance, and metastatic recurrence, with therapeutic targeting of ST6Gal-1-high triple-negative breast cancer stem cells demonstrating improved efficacy through glycan engineering approaches." (PMID 41154604, 2025).
ulcerative colitis (2 papers, 2023 to 2024). An inflammatory bowel disease involving the mucosal surface of the large intestine and rectum. "However, the role of ST6GAL1 in the pathogenesis of ulcerative colitis (UC) remains unknown." (PMID 37424034, 2023). "Ablation of ST6GAL1 attenuates the TCR signaling, downregulates the expression of NF‐κB and reduces the production of proinflammatory cytokines, and relieves ulcerative colitis (UC) pathogenesis." (PMID 37424034, 2023).
arteriosclerosis (1 paper, 2025). A vascular disorder characterized by thickening and hardening of the walls of the arteries. "Two key hub genes (CX3CR1 and ST6GAL1) were identified as biomarkers for arteriosclerosis in bipolar disorder patients." (PMID 41141090, 2025).
astrocytoma (1 paper, 2021). "Our findings suggest that the ST6GAL1-rs2239611 polymorphism is significantly correlated with astrocytoma susceptibility and prognosis." (PMID 33836687, 2021). "Firstly, we just selected two SNPs of the ST6GAL1 and CYP19A1 genes associated with astrocytoma risk, and more SNPs in ST6GAL1 and CYP19A1 are needed to detect." (PMID 33836687, 2021). "We found that the ST6GAL1-rs2239611 significantly decreased the risk of astrocytoma in the codominant model (p = 0.044) and dominant model (p = 0.049)." (PMID 33836687, 2021). "In our case-control study, we found that ST6GAL1-rs2239611 is associated with a decreased risk but the significantly poorer prognosis of astrocytoma." (PMID 33836687, 2021). "In addition, the results of Cox regression analysis showed that the ST6GAL1-rs2239611 and -rs1042757 polymorphisms were significantly correlated with the prognosis of astrocytoma." (PMID 33836687, 2021). "Besides, ST6GAL1-rs2239611 AG or GG genotype was significantly associated with improved OS of astrocytoma (p = 0.026)." (PMID 33836687, 2021). "This study explored the correlations between ST6GAL1 and CYP19A1 gene polymorphisms and astrocytoma susceptibility and prognosis." (PMID 33836687, 2021). "In this case-control study, we mainly investigated the role of ST6GAL1 and CYP19A1 polymorphisms in the occurrence of astrocytoma." (PMID 33836687, 2021). "The correlation between ST6GAL1 and CYP19A1 variants and astrocytoma risk was calculated using logistic regression." (PMID 33836687, 2021). "Surgical methods, chemotherapy, and genotypes (ST6GAL1-rs2239611, −rs1042757) were the primary prognostic factors for astrocytoma (p < 0.05)." (PMID 33836687, 2021). "In this study, we investigated the correlation between ST6GAL1 and CYP19A1 polymorphisms and the risk and prognosis of astrocytoma." (PMID 33836687, 2021). "Based on these results, we suggested that ST6GAL1 played a pivotal role in astrocytoma development." (PMID 33836687, 2021). "Therefore, we selected four polymorphic sites of ST6GAL1 and CYP19A1 3’UTR to explore their impact on the risk and prognosis of astrocytoma." (PMID 33836687, 2021). "Our results suggest that ST6GAL1 and CYP19A1 genes may be a potential biomarker of genetic susceptibility and prognosis to astrocytoma in the Chinese Han population." (PMID 33836687, 2021). "In summary, our study provided evidence that ST6GAL1 and CYP19A1 genes contribute to the development of astrocytoma among Chinese Han people." (PMID 33836687, 2021). "Secondly, the molecular mechanism under which ST6GAL1 and CYP19A1 polymorphisms affect the risk and prognosis in astrocytoma is not elucidated." (PMID 33836687, 2021).
B-cell precursor acute lymphoblastic leukemias (1 paper, 2022). "B-cell precursor acute lymphoblastic leukemias (BCP-ALLs) with differentiation arrest at various stages of early B-cell development have widely different expression levels of ST6GAL1 at diagnosis, with high ST6Gal1 in some but not in other relapses." (PMID 35371997, 2022).
bladder (1 paper, 2014). "In the present study we aimed to describe for the first time ST6GAL1 expression and regulation in human bladder carcinogenesis." (PMID 25465919, 2014).
bladder tumors (1 paper, 2014). "A tight association between loss of ST6GAL1 mRNA expression and advanced bladder tumor stages (pT2-pT4; invasive subtype) was significantly underscored by using Fisher’s exact test." (PMID 25465919, 2014). "As such we frequently detected ST6GAL1 expression loss by 2.6-fold in pTa and by 3.4-fold in pT1/pT2 bladder tumors." (PMID 25465919, 2014). "In contrast methylated bladder tumors showed a significant (p < 0.05) reduction in ST6GAL1 mRNA expression down to 0.338." (PMID 25465919, 2014). "To begin, we revealed a differential ST6GAL1 mRNA expression in bladder tumors compared to normal urothelium." (PMID 25465919, 2014). "Importantly, a highly significant inverse correlation between ST6GAL1 expression and ST6GAL1 promoter hypermethylation was observed in these bladder tumors." (PMID 25465919, 2014). "In contrast, invasive bladder tumors were characterized by a decreased ST6GAL1 protein staining: 69.2% (n = 45/65) of all analyzed tumors showed an ST6GAL1 protein staining of IRS ≤ 4 and 25.6% (16/65) exhibited an almost complete loss (IRS = 0) of ST6GAL1 protein." (PMID 25465919, 2014). "ST6GAL1 mRNA in both normal-like UROtsa and RT4 bladder tumor cells harboring an unmethylated ST6GAL1 promoter served as control and were not further inducible by DAC/TSA." (PMID 25465919, 2014).
breast tumor (1 paper, 2022). "Here, we examine the molecular contribution of ST6GAL1, particularly the ST6GAL1 in the extracellular spaces, on breast tumor cells." (PMID 35676533, 2022). "We found that shRNA knockdown of intrinsic ST6GAL1 expression resulted in decreased ST6GAL1 cargo in the exosome-like vesicles as well as decreased breast tumor cell growth and invasive behavior in 3D in vitro cultures." (PMID 35676533, 2022). "We confirm that cancer ST6GAL1 is variably expressed in triple-negative breast cancer (TNBC) clinical specimens that confer heterogeneous presence of α2,6-sialic acids on aggressive breast tumors." (PMID 35676533, 2022).
carcinoma in situ (1 paper, 2014). "ST6GAL1 mRNA expression levels in human cell lines (UROtsa, RT4, RT112 and J82) and tissue samples (n = 15 normal urothelium (NU), n = 13 papillary non-invasive tumors (pTa), n = 12 carcinoma in situ (CIS), n = 26 muscle invasive tumors (pT2-4)) were assessed using real-time PCR." (PMID 25465919, 2014).
colon inflammation (1 paper, 2023). "St6gal1 deficiency reduces the levels of pro‐inflammatory cytokines and alleviates colitis symptoms in UC model rats." (PMID 37424034, 2023). "Conversely, the transfer of CD4+ T cells from St6gal1+/+ UC rats aggravated the symptoms of colon inflammation." (PMID 37424034, 2023). "The colitis symptoms could be alleviated by St6gal1 ablation, resulting in decreased proliferation and activation of CD4+ T‐cells cells." (PMID 37424034, 2023).
fatty liver disease (1 paper, 2025). A reversible condition wherein large vacuoles of triglyceride fat accumulate in liver cells via the process of steatosis. "Furthermore, liver-specific depletion of ST6GAL1 has been associated with fatty liver disease, highlighting sialylation as a key regulator of lipid turnover in hepatocytes." (PMID 40180213, 2025).
follicular thyroid cancer (1 paper, 2023). "We performed an immunohistochemical analysis using human thyroid tissue from 89 patients and analyzed ST6GAL1 protein expression in papillary thyroid cancer (including follicular variant and microcarcinoma) and follicular thyroid cancer in comparison to normal thyroid tissue." (PMID 38003522, 2023).
Graves disease (1 paper, 2023). Graves' disease is an autoimmune disorder that leads to overactivity of the thyroid gland (hyperthyroidism).It is caused by an abnormal immune system response that causes the thyroid gland to produce too much thyroid hormones. "An increase in ST6GAL1 mRNA levels was also observed in other thyroid pathologies such as Graves’ disease (GD)." (PMID 38003522, 2023).
lupus (1 paper, 2016). "The higher ST6Gal-1 level and ST6Gal-1/Neu1 ratio in B cells potentially suggest greater lupus activity, due to their compatibility with low complement levels, pending for a large-population study to support it." (PMID 26981635, 2016). "Third, B-cell ST6Gal-1 levels and ST6Gal-1/Neu1 ratios may indicate the presence of lupus activity pending further exploration, due to the correlations of these variables with low serum C3c and C4 levels." (PMID 26981635, 2016). "Hence, ST6Gal-1 and Neu1 levels, and ST6Gal-1/Neu1 ratios were paralleled in various blood cells from individual lupus patients." (PMID 26981635, 2016). "Fourth, the positive correlations of ST6Gal-1 and Neu1 levels on B, T, and PMN cells and monocytes in lupus, both overall and in individuals, is likely a new finding with unexplained reasons." (PMID 26981635, 2016).
meningioma (1 paper, 2024). A generally slow growing tumor attached to the dura mater. "In the GEO database, mRNA expression of ST3GAL4 was significantly decreased in grade II and III meningiomas (P < 0.05), while the others (ST3GAL1, ST3GAL3, ST3GAL6, ST6GAL1, and ST6GALNAc1) were not." (PMID 38274327, 2024).
oesophageal adenocarcinoma (1 paper, 2024). "Twenty-two proteins were associated with the risk of oesophageal cancer and/or oesophageal adenocarcinoma, including REG4 and ST6GAL1 [2.02 (1.66–2.45) and 1.83 (1.53–2.19)]." (PMID 38750076, 2024).
papillary thyroid cancer (1 paper, 2023). "Notably, the follicular variant of papillary thyroid cancer exhibited significantly higher ST6GAL1 mRNA levels than classic papillary thyroid cancer." (PMID 38003522, 2023).
prion disease (1 paper, 2022). A transmissible disease that is caused by a protein that is able to induce abnormal folding of normal cellular proteins, leading to characteristic spongiform brain changes, which are associated with neuronal loss without an inflammatory response. "Alternatively, deficiency in ST6Gal1 could affect the incubation time by altering homeostatic and/or reactive states of peripheral immune cells involved in prion disease pathogenesis." (PMID 36452458, 2022). "The current study tested whether a deficiency of ST6Gal1 reduces the sialylation status of PrPSc and alters prion disease pathogenesis." (PMID 36452458, 2022). "Histopathological analysis showed the main pathological hallmarks of prion disease including PrPSc deposition, spongiosis and reactive microglia in both ST6Gal1-KO and control WT mice." (PMID 36452458, 2022). "It would be interesting to test whether a knockout of ST6Gal2 or a double knockout of ST6Gal1 and ST6Gal2 affect prion disease pathogenesis." (PMID 36452458, 2022). "Because reactive astrocytes associated with prion disease are detrimental to neurons, the delay in the incubation time could be attributed to an attenuation of a STAT3-mediated activation of astrocytes in ST6Gal1-KO mice." (PMID 36452458, 2022). "The current study tests whether a knockout of ST6Gal1, one of the two mammalian sialyltransferases that catalyze the sialylation of glycans via α2-6 linkages, reduces the sialylation status of PrPSc and alters prion disease pathogenesis." (PMID 36452458, 2022).
rectal adenocarcinoma (1 paper, 2022). "Our study is the first to examine the role of ST6GAL-1 in resistance to chemoradiation in human rectal adenocarcinomas and PDX models and to assess the mechanism of resistance." (PMID 35041825, 2022). "In order to assess the distribution of ST6GAL-1 protein within individual tumors, we performed immunostaining in untreated human rectal adenocarcinoma samples and normal rectal tissues." (PMID 35041825, 2022). "ST6GAL-1 mRNA was assessed in untreated human rectal adenocarcinoma by PCR assays." (PMID 35041825, 2022). "We hypothesized that ST6GAL-1 may mediate resistance to chemoradiation in rectal adenocarcinoma by decreasing apoptosis." (PMID 35041825, 2022). "We found that ST6GAL-1 protein was only in a subset of cells within the base of the crypts (stem cell compartment) of the normal tissues (similar to prior work), but that in the human rectal adenocarcinoma samples, ST6GAL-1 was in some but not in all the adenocarcinoma cells in any given tumor." (PMID 35041825, 2022).
serous ovarian carcinoma (1 paper, 2019). "For instance, the rates of SOX2 and ST6GAL1 CNG within the ovarian serous carcinoma cohort (*) are 27 and 24%, respectively." (PMID 31610800, 2019).
thyroid autoimmunity (1 paper, 2022). "Due to the documented activity of serum ST6Gal1 from AITD patients on desialylated IgG N-glycans, we suppose that this serum sialyltransferase may contribute to IgG sialylation in the bloodstream in thyroid autoimmunity." (PMID 35370997, 2022).
thyroid diseases (1 paper, 2023). "Since Tg levels are altered in thyroid pathologies, in the current study, we wanted to analyze the ST6GAL1 protein expression in different types of well-differentiated thyroid cancers." (PMID 38003522, 2023).
thyroid tumor (1 paper, 2023). A benign or malignant neoplasm affecting the thyroid gland. "The analysis of ST6GAL1 protein expression in human thyroid tumors revealed that expression in thyroid tumors is higher in comparison to normal thyroid tissue." (PMID 38003522, 2023). "The immunohistochemical analysis revealed higher ST6GAL1 protein expression in all thyroid tumors compared to normal thyroid tissue." (PMID 38003522, 2023). "We showed that expression of ST6GAL1 was increased in all examined thyroid tumors compared to normal thyroid tissue, with the highest expression in FVPTC." (PMID 38003522, 2023).
type 1 diabetes (1 paper, 2023). "In addition, decreased ST6GAL1 expression in B cells has been associated with type 1 diabetes risk-associated alleles." (PMID 36907892, 2023). "Decreased expression of ST6GAL1 (encoding ST6 beta-galactoside alpha-2,6-sialyltransferase 1) in B cells has been shown to be associated with type 1 diabetes risk-associated alleles." (PMID 36907892, 2023).